IGFBP7 (insulin like growth factor binding protein 7)
Diseases named in the same sentence as IGFBP7 in open-access papers (continued):
Sharing a sentence is not in itself a finding about the gene and the disease.
diabetes (27 papers, 2008 to 2025). "The main limitations of TIMP2*IGFBP7 are decreased diagnostic values in diabetes (possibility of false-positive measurements occurrence) and relatively high cost." (PMID 39596140, 2024). "Multiple studies have reported that IGFBP7 is closely associated with human insulin resistance, diabetes, lipid metabolism, and obesity." (PMID 38840498, 2024). "Top downregulated genes included those previously associated with diabetes and obesity, such as Manf and Creld2 that facilitate protein folding, and Igfbp3 and Igfbp7, two structurally similar proteins that regulate the bioavailability of IGFs and insulin." (PMID 36988733, 2023). "Recently, studies of chronic HF have shown that higher levels of IGFBP7 are associated with diabetes mellitus and obesity." (PMID 37009790, 2023). "Regardless of the mechanism, the results of the current study support the idea that IGFBP7 is associated with insulin resistance in non-insulin dependent diabetes mellitus patients." (PMID 19019211, 2008). "Researchers have discovered potential associations between type 2 diabetes mellitus and obesity and the biomarkers glucagon-like peptide-1, glucose-dependent insulinotropic peptide, monocyte chemoattractant protein-1, and insulin-like growth factor-binding protein-7." (PMID 38255264, 2024). "In addition, IGFBP-7 is associated with the severity of diastolic dysfunction; it is also involved in fibrogenesis in patients with diabetes." (PMID 31842522, 2019). "The findings from these studies indicated serum IGFBP7 might be associated with IR and diabetes." (PMID 25984973, 2015). "Models 1–4 individually assessed the effects of diabetes, eGFR, uTIMP‐2•IGFBP7/Cr and chronic injury scores." (PMID 40845179, 2025). "Given that IGFBP7 is upregulated in human pancreatic islets in type 2 diabetes, and that reversing this improves insulin secretion, IGFBP7 is emerging as a possible multi-tissue drug target in diabetes and other metabolic disorders." (PMID 39280605, 2024). "The biomarkers GLP-1, GIP, MCP-1, and IGFBP7 hold promise in improving diagnostics for diabetes and obesity." (PMID 38255264, 2024). "The presence of diabetes mellitus was strongly associated with higher levels of GDF-15 and to a lesser extent of IGFBP7." (PMID 34217226, 2021). "Finally, IGFBP7 knockdown in islets from T2D donors improved insulin secretion, making IGFBP7 a potential drug target in diabetes." (PMID 39280605, 2024). "There were some previous researches intended to examine association of IGFBP7 with IR and diabetes, however the findings were not consistence." (PMID 25984973, 2015). "Patients with pulmonary disease and diabetes had higher [TIMP-2]·[IGFBP7] levels on admission." (PMID 25866432, 2015). "In contrast to the Sapphire trial, we found an independent association between urinary [TIMP-2]·[IGFBP7] and diabetes, but not with evolving AKI." (PMID 25866432, 2015). "Diabetes was independently associated with higher [TIMP-2]·[IGFBP7] levels (P = 0.02) but AKI was not (P = 0.24)." (PMID 25866432, 2015). "Due to the high affinity to insulin, IGFBP7 may interfere with biological response of insulin, subsequently induces IR and involves in the development of diabetes and cardiovascular diseases." (PMID 25984973, 2015). "However, we found an independent association between diabetes and elevated [TIMP-2]·[IGFBP7] levels." (PMID 25866432, 2015). "Our observations suggest that IGFBP7 is associated with the pathophysiology of endometriosis and diabetes mellitus, and that serum IGFBP7 levels do not reflect enhanced uterine expression of IGFBP7 mRNA during the menstrual cycle." (PMID 19019211, 2008). "This suggests IGFBP-7 could compete with insulin receptors for insulin binding and interfere with the physiological response to insulin, contributing to insulin resistance and subsequently to development of diabetes and cardiovascular disease." (PMID 27769173, 2016).
diabetes (continued). "Neither a previous diabetes diagnosis nor laboratory parameters of glucose metabolism (glucose, insulin and C-peptide concentrations in an oral glucose tolerance test) were found to be independently associated with IGFBP7 concentration in the multivariate analysis." (PMID 35204773, 2022). "IGFBP-3, IGFBP-4, IGFBP-5, IGFBP-6 are involved in different kidney disease such as diabetes, FSGS and CKD physiological process as apoptosis proteins, IGFBP-7 has been used in clinical practice as a biomarker for early diagnosis and prognosis of AKI." (PMID 35002740, 2021). "Hemodialysis patients with diabetes had significantly higher serum IGFBP7 levels than hemodialysis patients without diabetes." (PMID 19019211, 2008). "However, large validation studies of the Nephrocheck test showed that urine [IGFBP7]*[TIMP-2] values were not elevated in patients with stable chronic morbidities such as diabetes mellitus, congestive heart failure and CKD who did not have AKI and were not affected by sex or age." (PMID 35207297, 2022). "Consequently, IGFBP-7 levels increase in diabetes patients with normal diastolic function, and in patients with diastolic dysfunction either with or without diabetes; the highest values of IGFBP-7 levels are found in patients with diastolic dysfunction and diabetes." (PMID 31842522, 2019). "Patients with type II diabetes mellitus (DM) had significantly higher IGFBP7 levels than non-DM patients." (PMID 19019211, 2008). "In the current study, the IGFBP-7/IGF-1 ratio was significantly increased in patients with metabolic syndrome and/or diabetes compared to those without metabolic syndrome." (PMID 27769173, 2016).
melanoma (27 papers, 2008 to 2025). A malignant, usually aggressive tumor composed of atypical, neoplastic melanocytes. "Wajapeyee and coworkers suggest that loss of IGFBP7 expression acts as a critical step in melanoma genesis." (PMID 23861977, 2013). "Recently, immunohistochemical analysis of human skin, nevi, and melanoma samples implicates loss of IGFBP7 expression as a critical step in melanoma carcinogenicity." (PMID 20158915, 2010). "Recent work identified several genes required for the BRAFV600E-induced senescence and showed that in the context of BRAF mutation, expression loss of one of them, IGFBP7, is critical in promoting the progression to melanoma." (PMID 20975957, 2010). "In particular the most significant up-regulated gene IGFBP3 is intriguing in the context that another member of the insulin-like growth factor binding protein family, IGFBP7 has recently been implicated as an inducer of apoptosis in human melanoma cell lines." (PMID 18714388, 2008). "Also, the expression of IGFBP7 in melanoma cells containing the BRAF mutation can induce cell senescence and apoptosis." (PMID 32500027, 2020). "IGFBP7 and Latexin (highest up- and downregulated expression in microarray analysis) were found to be associated with longer and shorter survival, respectively, of melanoma patients." (PMID 30089785, 2018). "Genome-wide RNA interference screening study revealed that loss of expression of insulin-like growth factor binding protein 7 (IGFBP7) is a critical step in development of a malignant melanoma (MM), and this secreted protein plays a central role in apoptosis of MM." (PMID 20158915, 2010). "Moreover, they observed loss of IGFBP7 in primary BRAFV600E-positive melanoma samples and concluded that silencing of IGFBP7 expression is a critical step in the development of a melanoma harboring BRAFV600E." (PMID 20027224, 2009). "The pronounced reduction of IGFBP7 expression in metastatic samples indicates that during the development of melanoma, there is a substantial selection against IGFBP7 expression." (PMID 32500027, 2020). "It has been reported that IGFBP7 inhibits the BRAF-MEK-ERK pathway in an autocrine or paracrine manner and causes apoptosis in BRAF mutation-positive melanoma cells." (PMID 31183073, 2019). "Patients whose melanoma displayed the IGFBP7 high staining pattern had a better prognosis (longer survival) in comparison to the IGFBP7 low patients (age-adjusted HR 0.32, 95%-CI [0.15;0.71]; p = 0.005)." (PMID 30089785, 2018). "Expression of insulin-like growth factor binding protein 7 (Igfbp-7) in melanoma cells was shown to inhibit cell growth due to apoptosis." (PMID 27270319, 2016). "In our study, we first found that up-regulation of IGFBP5 decreased HIF1α expression and the other IGFBPs family members, IGFBP2, IGFBP4, IGFBP6, and IGFBP7 to some extent in melanoma cells." (PMID 26010068, 2015). "In a tumor xenograft model, for example, the over-expression of IGFBP7 inhibited the growth of melanoma." (PMID 24427302, 2014). "Since then, IGFBP7 has received particular attention due to its potential to induce apoptosis in human melanoma cell lines." (PMID 21701676, 2011). "As a consequence, RAS is mutated in melanoma, the cells (B16-F10) switch their signaling from BRAF to CRAF, then IGFBP7 expression is decreased, enabling the cells to escape from senescence and resulting in uncontrolled proliferation." (PMID 20158915, 2010). "We demonstrated this plasmid inhibited proliferation of B16-F10 melanoma cells efficiently in vivo, exploiting the high expression of IGFBP7." (PMID 20158915, 2010). "Their subsequent findings suggest that IGFBP7 expression is both necessary and sufficient to induce senescence and apoptosis in human primary melanocytes and melanoma, respectively." (PMID 20027224, 2009). "Indeed, overexpression of IGFBP7 in B16-F10 melanoma cells downregulated the expression of VEGF (Chen R.-Y." (PMID 39045455, 2024).
melanoma (continued). "Treatment with recombinant exogenous IGFBP7 human melanoma cell lines carrying mutated BRAF can induce cell senescence and apoptosis, and systemically administrated in xenograft mouse models counteract melanoma growth." (PMID 37762344, 2023). "A major study found that IGFBP7 gene expression is missing in primary melanomas bearing an activating mutation of the B-Raf gene (BRAF) but apparently not in primary melanomas with wild-type BRAF." (PMID 32500027, 2020). "Therefore, all melanoma samples were classified into two groups: IGFBP7 high, meaning that nearly all tumor tissue displayed moderate or high IGFBP7 staining or IGFBP7 low, with at least 20% tumor tissue negative or only weakly positive for IGFBP7." (PMID 30089785, 2018). "IGFBP7 expression could be investigated by immunohistochemistry in melanoma from 101 patients of the same cohort as above." (PMID 30089785, 2018). "However, as the cell line used in this study is BRAF wildtype it is still possible that CEACAM1 signaling affects IGFBP7 expression in certain subsets of patients (e.g. patients with BRAF wildtype melanoma)." (PMID 30089785, 2018). "IGFBP-2, IGFBP-3 and IGFBP-7 expression was elevated in epithelial-like melanoma cells." (PMID 25940796, 2015). "In human melanocytes, senescence is associated with an increased production of insulin-like growth factor binding proteins (IGFBP), and treatment with recombinant exogenous IGFBP7 is sufficient to induce senescence in melanocytes and apoptosis in certain melanoma cell lines." (PMID 23555779, 2013). "Intriguingly, IGFBP7 was shown to be epigenetically silenced by CpG island promoter hypermethylation specifically in primary melanoma samples carrying BRAFV600E, indicating that loss of IGFBP7 expression is critical in the development of BRAFV600E-positive melanoma." (PMID 20027224, 2009). "This new finding implies that IGFBP7 may have a potential therapeutic role in curing melanoma." (PMID 32500027, 2020). "Interestingly, the IGFBP7 gene is often silenced by epigenetic mechanisms in primary melanomas, and might thereby contribute to early malignant transformation of malignant melanoma." (PMID 19642975, 2009). "The markers CEACAM1, FOSL1, IGFBP7, LXN and cytoplasmic/nuclear TWIST were used as predictors in a multivariate Cox model (adjusted for age) for the prognosis of the melanoma patients’ survival." (PMID 30089785, 2018). "IGFBP-rP1 (IGFBP7) was described to have a central role in BRAF-mediated senescence and apoptosis in melanoma cells." (PMID 20924377, 2010). "Moreover, novel interactions between tumor-secreted IGFBP-7 and CD93 on endothelial cells led to reduced angiogenesis and slowed tumor growth in in vitro models of melanoma, confirming the role of IGFBP-7:CD93 interactions in tumor development." (PMID 41226289, 2025). "implanted murine melanoma tumors with and without transfected IGFBP7 and found that IGFBP7 tumors had significantly more intratumoral vessels on immunostaining." (PMID 38468017, 2024). "CEACAM1 staining in a certain area of an individual melanoma sometimes correlated with IGFBP7 staining intensity in the same area, but more often did not (serial sections)." (PMID 30089785, 2018). "Following the results from the xenograft experiment, we hypothesized that melanoma cells with no or weak IGFBP7 expression have a higher metastatic potential than IGFBP7 high cells." (PMID 30089785, 2018). "Furthermore, they found a high level of IGFBP-7 expression in BRAF mutant nevi and undetectable levels in BRAF mutant melanomas, suggesting that this protein may act as a tumor-suppressor in melanoma." (PMID 19025658, 2008). "In the melanoma samples, high expression of CEACAM1 did not correlate with low IGFBP7 expression and low IGFBP7 expression did not correlate with high LXN expression (φ = −0.01, p = 0.911 and φ = 0.03, p = 0.781, respectively)." (PMID 30089785, 2018).
colorectal cancer (25 papers, 2009 to 2026). A primary or metastatic malignant neoplasm that affects the colon or rectum. "IGFBP7 expression was also linked to a poor prognosis in multiple myeloma, colorectal cancer, esophageal adenocarcinoma, and head and neck squamous cell carcinomas." (PMID 30609749, 2019). "In contrast, IGFBP7 expression has also been associated with poorest outcome of patient with oesophagial adenocarcinoma or colorectal cancer." (PMID 25886299, 2015). "Several studies have demonstrated that increased DNA methylation levels of the IGFBP7 gene are associated with colorectal cancers and lung and prostate cancer." (PMID 24180466, 2013). "Studies indicated that the exposure of tumor suppressors such as mitomycin C and IGFBP7 to cervical and colorectal carcinoma cells caused down-regulation of HSP60." (PMID 22363243, 2011). "Promoter-associated CpG island DNA hypermethylation of IGFBP7 has been reported in human colorectal cancer cell lines as well." (PMID 20027224, 2009). "Interestingly, mechanistic studies of colorectal cancer have shown that knockdown of IGFBP7 impacts proteins associated with EMT, such as downregulation of E-cadherin." (PMID 34606580, 2021). "Moreover, we found that IGFBP7 DNA hypermethylation is associated with loss of expression in CIMP+ colorectal cancer cell lines." (PMID 20027224, 2009). "When SW480 colorectal cancer cells were co-cultured with fibroblasts, IGFBP7 expression was induced in fibroblasts at both the mRNA and protein levels." (PMID 37296997, 2023). "High expressions of serum IGFBP7 protein were also found in high-grade soft tissue sarcoma, colorectal cancer, esophageal squamous cell carcinoma, and esophagogastric junction adenocarcinoma." (PMID 37304887, 2023). "Evidence suggests that IGFBP7 acts as an oncosuppressor gene in prostate, breast, lung, and colorectal cancer due to its regulatory action related to cell proliferation, cell adhesion, cell senescence, and angiogenesis." (PMID 36658131, 2023). "IGFBP7 was identified as a tumor stroma marker of epithelial cancers, and stromal expression of IGFBP7 was an indicator of poor survival in colorectal cancer." (PMID 37296997, 2023). "The expression of IGFBP7 is an independent prognostic indicator of decreased survival in esophageal and colorectal cancer patients." (PMID 37568781, 2023). "Insulin-like growth factor-binding protein 7 (IGFBP7) is known as a tumor suppressor for colorectal cancer (CRC)." (PMID 35836256, 2022). "Insulin-like growth factor binding protein 7 (IGFBP7) is known as a tumor suppressor in colorectal cancer (CRC)." (PMID 24427302, 2014). "In our previous study, it was well defined that IGFBP7 was an important tumor suppressor gene in colorectal cancer (CRC)." (PMID 20433702, 2010). "On one hand IGFBP7 has recently been described as a tumour suppressor gene in colorectal cancer and was shown to induce senescence in cells harbouring oncogenic BRAF, whereas on the other hand IGFBP7 was shown to have oncogenic properties in gliomas." (PMID 20579385, 2010). "Our group presented evidence that reintroduction of IGFBP7 suppressed the proliferation, decreased the colony formation ability, and induced apoptosis in two colorectal carcinoma cell lines RKO and SW620." (PMID 20433702, 2010). "The DNA methylation inhibitor 5-aza-2′-deoxycytidine has been shown to restore IGFBP7 expression in colorectal cancer cell lines, indicating that the DNA hypermethylation plays a major role in silencing of this gene in colorectal cancer." (PMID 20027224, 2009). "Interestingly, previous studies of IGFBP7’s role in colorectal cancer have documented its potential function as a paracrine signaling molecule in the tumor-stroma crosstalk." (PMID 39233736, 2024). "Moreover, IGFBP7+ patients have an early recurrence within 12 months after surgery and a shorter survival time, and a worse prognosis than IGFBP7- patients with colorectal cancer." (PMID 37660019, 2023).